TXNDC5 (thioredoxin domain containing 5)
Diseases named in the same sentence as TXNDC5 in open-access papers (continued):
Sharing a sentence is not in itself a finding about the gene and the disease.
glioma (3 papers, 2020 to 2022). A benign or malignant brain and spinal cord tumor that arises from glial cells (astrocytes, oligodendrocytes, ependymal cells). "The detailed analysis of TXNDC5 in glioma pathogenesis revealed that TXNDC5 expression is associated with more aggressive clinical and molecular features and poor therapy success both in LGG and GBM samples." (PMID 36106447, 2022). "In order to validate this finding in a glioma setting we have also performed a correlation analysis between TXNDC5 and the ECM‐encoding gene transcripts that are known to be involved in glioma progression." (PMID 36106447, 2022). "Altogether, TXNDC5 expression was found to be associated with aggressive tumor characteristics and therapy resistance which in turn may promote glioma propagation." (PMID 36106447, 2022). "The increased TXNDC5 levels in gliomas prompted us to investigate the molecular mechanism regulating TXNDC5 expression." (PMID 36106447, 2022). "Overall, TXNDC5 was determined to be a potential prognostic marker and target for therapy in glioma patients." (PMID 36106447, 2022). "Our findings suggested that TXNDC5 can be used as a therapy target and prognostic marker in glioma; however, further studies are warranted." (PMID 36106447, 2022). "Our analysis revealed that TXNDC5 levels are elevated in glioma samples and its increment is correlated with an aggressive phenotype, low therapy success and poor prognosis." (PMID 36106447, 2022). "To clarify hypoxia's impact on TXNDC5 expression in a glioma microenvironment, we have performed a correlation analysis between tumor hypoxia scores and TXNDC5 transcript levels." (PMID 36106447, 2022). "To understand the possible mechanism lying behind TXNDC5‐directed glioma progression we performed a GO enrichment analysis." (PMID 36106447, 2022). "To verify the possible regulation of TXNDC5 by ER stress in all grade gliomas, we performed a correlation analysis." (PMID 36106447, 2022). "The levels of TXNDC5 was shown to be possibly regulated by hypoxia‐ER stress axis and a potential mechanism for TXNDC5‐driven glioma progression was found to be extracellular matrix (ECM) production which is known to promote tumor aggressiveness." (PMID 36106447, 2022). "In the present study, we have uncovered the previously unknown role of TXNDC family members, in particular TXNDC5, in glioma progression." (PMID 36106447, 2022). "Last but not least, increased TXNDC5 levels in all grade glioma patients were strongly associated with poor OS, DSS and PFI." (PMID 36106447, 2022). "We also wanted to explore TXNDC5 levels in different molecular subtypes of gliomas." (PMID 36106447, 2022). "Our GO enrichment analysis indicates additional mechanisms may be responsible for TXNDC5‐driven glioma propagation." (PMID 36106447, 2022). "Overall, we have confirmed that TXNDC5 plays a pivotal role in malignant progression of glioma." (PMID 36106447, 2022). "Altogether, our data imply that TXNDC5 may help glioma progression via activation of anti‐apoptotic pathways under stress conditions." (PMID 36106447, 2022). "Indeed, TXNDC5 levels showed strong correlation with mesenchymal markers verifying its role in EMT process for glioma as well." (PMID 36106447, 2022). "Our results uncovered the previously unknown role of TXNDC family members in glioma pathogenesis and showed that TXNDC5 levels could serve as a predictor of clinical outcome and therapy success and may very well be used for targeted therapy." (PMID 36106447, 2022). "The data so far indicate that TXNDC5 may have a prognostic value in glioma patients." (PMID 36106447, 2022). "Our data revealed that TXNDC1, TXNDC5, and TXNDC7 transcript levels were significantly higher in all grade gliomas compared to healthy brain tissue." (PMID 36106447, 2022). "Moreover, TXNDC5 transcript levels was an independent prognostic factor of overall survival (OS), disease free survival (DFS), and progression free interval (PFI) in LGG and all grade gliomas." (PMID 36106447, 2022).
glioma (continued). "Our analysis revealed that tumors with high progressive capacity have elevated levels of TXNDC5 in LGG and all grade glioma patients while TXNDC5 expression did not change with progressive phenotype in GBM group." (PMID 36106447, 2022).
liver fibrosis (3 papers, 2022 to 2024). "TXNDC5 promotes hepatic stellate cell activity and ECM through JNK and STAT3 signaling, thereby causing liver fibrosis (LF)." (PMID 38629066, 2024). "TXNDC5 is significantly expressed in activated hepatic stellate cells (HSCs) and at the fibrotic foci of the livers of human patients and mice with liver fibrosis/cirrhosis." (PMID 38666927, 2024). "Finally, the role of TXNDC5 in the progression of liver fibrosis (LF) has recently been investigated." (PMID 38666927, 2024). "Taken together, targeting TXNDC5 may build a new avenue for liver fibrosis/cirrhosis treatments via blocking HSC activation, proliferation, ECM production, as well as depriving anti-apoptotic capacity of HSCs." (PMID 36050716, 2022).
melanoma (3 papers, 2021 to 2025). A malignant, usually aggressive tumor composed of atypical, neoplastic melanocytes. "Analysis of the underlying mechanism of METTL3 suggested that it affected melanoma cell growth and invasion by regulating TXNDC5." (PMID 35117988, 2021). "Meanwhile, we validated TXNDC5 higher expression in melanoma cell lines and melanoma tissues compared with HEMa and adjacent normal tissues, respectively." (PMID 35117988, 2021). "According to The Cancer Genome Atlas (TCGA) melanoma dataset, intratumoral TXNDC5 expression was positively correlated with METTL3 expression." (PMID 35117988, 2021). "Downregulated molecules include MMP2 and N-cadherin, both of which are necessary for melanoma metastasis and invasion, TXNDC5, which increases cell proliferation potential, and UCK2, which enhances melanoma cell migration via the Wnt/β-catenin signaling pathway." (PMID 41157107, 2025). "Taken together, TXNDC5 may be the downstream target of METTL3-m6A in melanoma and may play an important role in melanoma carcinogenesis." (PMID 35117988, 2021). "Similarly, the enhanced protein expression of TXNDC5 was also confirmed in melanoma tissues and cell lines." (PMID 35117988, 2021). "TXNDC5 is downregulated by decreasing N6-methyladenosine (m6A) levels as a post-transcriptional modification in RNA after METTL3 knockdown, ultimately inhibiting melanoma progression." (PMID 38666927, 2024). "This suggests that TXNDC5 may be the downstream target of METTL3-m6A in melanoma and may play an important role in melanoma carcinogenesis." (PMID 38666927, 2024).
myeloma (3 papers, 2017 to 2022). "Analogously, the high expression of TXNDC5 in plasma cells of bortezomib-resistant refractory/relapsed multiple myeloma (RRMM) patients suggests that TXNDC5 may be a bortezomib resistance marker or a potential RRMM treatment target." (PMID 35934705, 2022). "However, TXNDC5 is clearly over-expressed in myeloma samples when compared to normal plasma cells (Student two-sided t-test P-value < 10 e–5)." (PMID 29196615, 2017).
osteosarcoma (3 papers, 2017 to 2026). A usually aggressive malignant bone-forming mesenchymal neoplasm, predominantly affecting adolescents and young adults. "We previously detected significantly decreased cell proliferation using the CCK-8 kit and by assessing migratory ability of U2OS osteosarcoma cells and HeLa cells following treatment with anti-TXNDC5 siRNA using the Transwell migration assay." (PMID 29207620, 2017). "Furthermore, PIT1 co-localized with TXNDC5 is required for ER homeostasis, chondrocyte survival, and skeletal development, also TXNDC5 knockdown is highly toxic to osteosarcoma cells, possibly implying that it has a critical function in cells that endogenously express collagen-I." (PMID 38666927, 2024).
breast carcinoma (2 papers, 2017 to 2024). "Using this antagonist, ITGB1 and TXNDC5 proteins were downregulated, and similar results were observed for the induction of NR4A1-responsive genes CDKN1A, SERPINB5 and GADD45α in breast cancer MDA-MB-231 and SKBR3 cells." (PMID 38666927, 2024). "In mouse vascular smooth muscle cells (VSMC) and breast cancer cells (MCF-7), the protein abundance of TXNDC5 was significantly decreased by moRNA-21 but not miRNA-21, indicating that some genes are specifically regulated only by miRNA or moRNA-21." (PMID 38666927, 2024).
cervical squamous cell carcinoma (2 papers, 2017 to 2024). A squamous cell carcinoma arising from the cervical epithelium. "Immuno-reactive score analysis also detected significantly increased TXNDC5 expression in cervical squamous cell carcinomas compared with the corresponding adjacent normal tissues with or without inflammation." (PMID 29207620, 2017). "In the current study, we observed extensive immunostaining of TXNDC5 in all cervical squamous cell carcinoma tissue samples." (PMID 29207620, 2017). "They point out that TXNDC5 is highly expressed in cervical squamous cancer tissues." (PMID 38629066, 2024). "In addition, some mesenchymal cells in cervical squamous cell carcinoma tissues exhibited significant TXNDC5 expression, and stronger immunostaining was noted compared with tumor cells." (PMID 29207620, 2017). "TXNDC5 was expressed in all 22 (100%) cervical squamous cell carcinomas." (PMID 29207620, 2017). "Immuno-reactive score analysis was performed, revealing significantly increased TXNDC5 expression in cervical squamous cell carcinomas compared with the corresponding adjacent normal tissues with chronic inflammation (p = 0.005) and normal tissues without inflammation (p = 0.002)." (PMID 29207620, 2017).
cervical tumor (2 papers, 2017 to 2024). "A significant association was found between the rs408014 and rs7771314 SNPs at the TXNDC5 locus and cervical tumor susceptibility." (PMID 38666927, 2024). "We further investigated the pathogenic mechanism of TXNDC5 in HeLa cells that originated from a cervical tumor." (PMID 29207620, 2017). "TXNDC5 contributes to the process of vasculogenic mimicry, cell migration and cell proliferation of cervical tumors by down-regulating SERPINF1 and TRAF1 expression." (PMID 29207620, 2017). "Immunohistochemistry was performed to determine TXNDC5 expression in a panel of cervical tumor tissues." (PMID 29207620, 2017). "The results from the previous studies and those from the current study confirmed the increased expression of TXNDC5 in cervical tumor tissue." (PMID 29207620, 2017). "Western blot analysis using an anti-TXNDC5 antibody detected a 48-kDa band in the tissue extracts of all 7 cervical tumor samples." (PMID 29207620, 2017). "Western blot analysis also demonstrated a significant increase in TXNDC5 expression in cervical tumor tissues compared with uterine myoma samples." (PMID 29207620, 2017). "We also detected a significantly increased expression of TXNDC5 in cervical tumor tissues using immunohistochemistry and Western blot analysis." (PMID 29207620, 2017). "However, TXNDC5 exhibits increased expression in cervical tumors, other tumor tissues and various tumor cell lines." (PMID 29207620, 2017). "Additionally, inhibition of TXNDC5 expression using siRNA prevented tube-like structure formation, an experimental indicator of vasculogenic mimicry and metastasis, in HeLa cervical tumor cells." (PMID 29207620, 2017).
clear cell renal cell carcinoma (2 papers, 2022 to 2024). "In addition, knockdown of TXNDC5 can result in clear cell renal cell carcinoma cells sensitive to chemotherapy drugs such as 5-fluorouracil and camptothecin and suppress the growth, migration, and invasion of clear cell renal cell carcinoma cells." (PMID 39275334, 2024).
endometrial cancer (2 papers, 2024). Primary or metastatic malignant neoplasm involving the endometrium (mucous membrane that lines the endometrial cavity). "In endometrial cancer cells where NR4A1 is silenced, the major source of ROS is associated with the downregulation of TXNDC5 and IDH1." (PMID 39000233, 2024). "Therefore, the inhibition of mTOR signaling in endometrial cancer by NR4A1 antagonists is largely attributed to the downregulation of TXNDC5 and the consequent induction of ROS." (PMID 38666927, 2024).
fibrosis (2 papers, 2020 to 2024). the formation of excess fibrous connective tissue in an organ or tissue in a reparative or reactive process. "That study suggested that TXNDC5 promotes cardiac fibrosis primarily through redox-dependent cardiac fibroblast activation and enhances ECM production by boosting ECM protein folding." (PMID 39701940, 2024).
hyperlipidemia (2 papers, 2022 to 2024). "Various studies have shown that both DF and hyperlipidemia have a significant impact on the endothelial expression of TXNDC5, and also TXNDC5 mediates TNF-α-induced NOX activation in ECs." (PMID 38666927, 2024). "Endothelium-specific deletion of Txndc5 also markedly increased eNOS expression in the ligated LCA in Txndc5∆ECKO, compared with that in control (Cdh5-Cre/ERT2), mice with hyperlipidemia induced by PCSK9 overexpression and HFD." (PMID 35061532, 2022).
Insulin resistance (2 papers, 2024). Increased resistance towards insulin, that is, diminished effectiveness of insulin in reducing blood glucose levels. "By clarifying the specific functions of TXNDC5 in metabolism, researchers may discover new therapeutic strategies for managing conditions such as obesity, insulin resistance, and type 2 diabetes." (PMID 38666927, 2024).
Myocardial fibrosis (2 papers, 2020 to 2025). "Additionally, knockout of the endoplasmic reticulum protein TXNDC5 has been shown to inhibit JNK pathway activation, resulting in decreased expression of fibrosis-associated proteins, reduced myocardial fibrosis, and improved cardiac functional performance." (PMID 41150746, 2025).
osteoarthritis (2 papers, 2011 to 2022). A noninflammatory degenerative joint disease occurring chiefly in older persons, characterized by degeneration of the articular cartilage, hypertrophy of bone at the margins and changes in the synovial membrane. "In 2009, our research group found that TXNDC5 was specifically expressed in the tissues of RA patients compared with osteoarthritis and ankylosing spondylitis." (PMID 35934705, 2022). "The expression of TXNDC5 in tissues is positively correlated with the histological inflammatory score of osteoarthritis, chronic pyrophosphate arthropathy and RA." (PMID 35934705, 2022). "Real-time PCR, Western blotting and immunohistochemistry detected significantly higher TXNDC5 expression in the synovial tissues of RA patients compared to samples from patients with osteoarthritis (OA) or AS." (PMID 21801346, 2011).
renal fibrosis (2 papers, 2023 to 2024). A final common manifestation of a wide variety of chronic kidney diseases characterized by glomerulosclerosis and tubulointerstitial fibrosis. "A recent study showed that TXNDC5 regulates the TGFβ/ATF6/TGFβR1 signaling axis in renal fibrosis (RF), similar to what is observed in PF." (PMID 38666927, 2024). "In summary, these results suggest that targeting TXNDC5 could be a novel and powerful approach to treating or preventing renal fibrosis and RCC." (PMID 38666927, 2024).
Sepsis (2 papers, 2024 to 2025). Sepsis is defined as life-threatening organ dysfunction caused by a dysregulated host response to infection. "Further research has found that inhibition of TXNDC5 attenuated-induced sepsis by suppressing the NF-κB signaling pathway." (PMID 38629066, 2024). "In sepsis, RA and many other inflammatory diseases, TXNDC5 mediates the expression of a variety of inflammatory factors and receptors, which promotes the inflammatory response that leads to disease." (PMID 38629066, 2024). "TXNDC5 was found to be upregulated in lipopolysaccharide (LPS) induced sepsis." (PMID 38629066, 2024).
systemic lupus erythematosus (2 papers, 2011 to 2022). An autoimmune multi-organ disease typically associated with vasculopathy and autoantibody production. "ELISA detected significantly higher levels of TXNDC5 in the blood of RA patients compared to OA, AS and systemic lupus erythematosus patients, and healthy controls." (PMID 21801346, 2011).
acral melanoma (1 paper, 2021). "We also found that TXNDC5 served as a novel target of METTL3-m6A axis in acral melanoma." (PMID 35117988, 2021). "Further molecular mechanism investigation indicated that TXNDC5 was downregulated by decreasing m6A-levels after METTL3 knockdown and ultimately inhibiting the progression of primary acral melanoma." (PMID 35117988, 2021).
Alzheimer disease (1 paper, 2024). A progressive, neurodegenerative disease characterized by loss of function and death of nerve cells in several areas of the brain leading to loss of cognitive function such as memory and language. "Additionally, understanding TXNDC5’s influence on neurodegenerative processes may provide insights into the development of treatments for conditions such as Alzheimer’s disease, Parkinson’s disease, and others." (PMID 38666927, 2024).
and-neck carcinoma (1 paper, 2024). "In this report, three stressors have been utilized: tunicamycin, an inhibitor of GlcNAc phosphotransferase, causes a significant accumulation of unfolded proteins, activates the UPR, increases Txndc5, and ultimately results in cell death by apoptosis in human head-and-neck carcinoma cells." (PMID 39000233, 2024).
asthma (1 paper, 2025). "ITM2C, TXNDC5, and TXNDC11, though less studied in asthma, are involved in the endoplasmic reticulum secretory machinery of plasma cells, coordinating protein folding, quality control, and trafficking to support high-rate antibody synthesis and secretion." (PMID 40950420, 2025).
astrocytomas (1 paper, 2022). "Our results revealed that TXNDC5 levels were highest in the astrocytoma subtype." (PMID 36106447, 2022). "In addition, TXNDC5 showed the highest expression in astrocytoma indicating that it might play a role in LGG progression, especially in astrocytomas." (PMID 36106447, 2022).
autoimmune disease (1 paper, 2025). A disorder resulting from loss of function or tissue destruction of an organ or multiple organs, arising from humoral or cellular immune responses of the individual to their own tissue constituents. "TXNDC5 is overexpressed under hypoxic conditions and autoimmune diseases, functions as a stress survival factor, and is involved in angiogenesis in response to TNF-α and in the inflammatory response through the NF-κB signaling pathway." (PMID 39859202, 2025).
chronic kidney disease (1 paper, 2022). Impairment of the renal function secondary to chronic kidney damage persisting for three or more months. "Since TXNDC5 is a key player in the development of cardiac fibrosis and has been shown to be highly expressed in kidney fibroblasts, it is reasonable to assume that targeting TXNDC5 in the treatment of kidney fibrosis and chronic kidney disease (CKD) could have therapeutic benefits." (PMID 35497880, 2022).
COVID-19 (1 paper, 2024). A disease caused by infection with severe acute respiratory syndrome coronavirus 2. "Other studies have identified an upregulation of TXNDC5 in Parkinson’s disease, respiratory distress syndrome following cardiopulmonary bypass, COVID-19, malaria, Salmonella enteritidis and Marek’s disease infection." (PMID 38666927, 2024). "However, TNFRSF17 and TXNDC5 are the target genes for the COVID-19 vaccine." (PMID 38666927, 2024).
cutaneous squamous cell carcinoma (1 paper, 2023). "Proteins associated with inflammation, such as the SERPINA1 family and TXNDC5, are differentially positively altered in cutaneous squamous cell carcinoma and hepatocytes." (PMID 38138960, 2023).